NFE2L3 (NFE2 like bZIP transcription factor 3)
Diseases named in the same sentence as NFE2L3 in open-access papers (continued):
Sharing a sentence is not in itself a finding about the gene and the disease.
tumor (continued). "Notably, one of the key mechanisms by which NFE2L3 exerts its tumor-promoting effects is the regulation of cell cycle progression." (PMID 39149514, 2024). "Additionally, elevated NFE2L3 expression has been detected in B cells, monocytes, placental trophoblasts, and tumor cells." (PMID 39149514, 2024). "Taken together, we propose that NFE2L3 promotes CRC through changes in the tumor microenvironment, by suppressing the activity of Tregs and through the activation of mast cells, mediated, at least in part, via the increase of IL33 expression and decrease of RAB pathway signaling." (PMID 35091681, 2022). "Given the molecular differences between the proximal and distal parts of the colon and the dual role NFE2L3 plays, it would be of interest to assess whether NFE2L3 can serve as a prognostic factor while taking the position of the tumor into account." (PMID 35091681, 2022). "Knockdown of NFE2L3 showed a tumor-suppressive effect in liver and gastric cancer cells." (PMID 35846126, 2022). "The overexpression of NFE2L3 may promote tumorigenesis and progression by regulating tumor cell stemness and immune responses." (PMID 35846126, 2022). "However, the relationship between NFE2L3 DNA methylation and tumor progression requires further verification." (PMID 35846126, 2022). "Moreover, univariate Cox regression analysis revealed that the OS of patients with LIHC was significantly correlated with T stage, M stage, pathological stage, tumor status, and NFE2L3 expression." (PMID 35846126, 2022). "Furthermore, a prognostic nomogram using T stage, M stage, pathological stage, tumor status, and NFE2L3 was constructed to predict the one-, three-, and five-year OS in LIHC, which aids physicians in identifying patients at high risk for LIHC." (PMID 35846126, 2022). "In conclusion, NFE2L3 shows potential in tumor immunotherapy and may be a new target for tumor immunotherapy." (PMID 35846126, 2022). "However, knockdown of NFE2L3 enhanced the efficacy of lymphocyte-mediated tumor killing in the Kearney 2018 NK_10, Pech 2019 NK_E/T = 1, and Shifrut 2018 average cohorts." (PMID 35846126, 2022). "The methylation level of NFE2L3 was significantly correlated with different immune subtypes, suggesting that the methylation epistasis regulation of NFE2L3 may be involved in tumor immunity." (PMID 35846126, 2022). "A series of rescue experiments were performed to further verify whether NFE2L3 contributes to miR-23b-3p-mediated tumor-suppressive activity in COAD cells." (PMID 34966429, 2021). "We first detected cell proliferation by CCK-8, 24 hours after inoculation, the proliferation ability of sh1-NFE2L3 and sh2-NFE2L3 groups were lower than that of the control group, which suggested that NFE2L3 played a key role in the proliferation of tumor cells." (PMID 33123284, 2020). "Knockdown of NFE2L3 has been proved to inhibit the malignant behavior of tumor cells in vitro." (PMID 33123284, 2020). "LAT and NFE2L3 were upregulated in tumor samples, while HOXD3 was downregulated." (PMID 31777602, 2019). "NFE2L3 is not only involved in cell cycle regulation but also associated with apoptosis, proliferation, and inflammatory responses in tumor cells, suggesting that NFE2L3 might be involved in the apoptosis, proliferation and inflammatory responses of tumor cells." (PMID 40295497, 2025). "This suggests that NFE2L3 may play an essential role in tumor development." (PMID 35846126, 2022). "In addition, a nomogram model using T stage, M stage, pathological stage, tumor status, and NFE2L3 expression was constructed to predict the OS of patients in TCGA-LIHC cohort at one, three, and 5 years The calibration curve demonstrated that the model had good calibration." (PMID 35846126, 2022). "Therefore, through next-generation sequencing (NGS) of tumor tissues and detection of cfDNA in peripheral blood, NFE2L3 may serve as a potential marker for the diagnosis and prognosis prediction of patients with MPM." (PMID 35664314, 2022).
tumor (continued). "Nfe2l3−/− tumors were significantly enriched in the mid section of the colon (87%) compared to the other genotypes where tumors were more evenly distributed between the distal (45%) and mid sections (55%), suggesting location-based differences in tumor signaling." (PMID 35091681, 2022). "NFE2L3 may be involved in the occurrence of the EMT of tumor cells in vivo." (PMID 34783304, 2021). "In addition, tumor growth was inhibited by silencing of NFE2L3 in vivo." (PMID 33123284, 2020). "Thus all these data reveal that NFE2L3 could be instrumental in tumor migration by promoting both EMT process and the degradation of ECM." (PMID 33123284, 2020). "However, recent research, particularly in the past 5 years, has shed light on NFE2L3’s participation in diverse biological processes including cell differentiation, inflammatory responses, oxidative stress, lipid homeostasis, transcription activation, immune response, and tumor growth." (PMID 39149514, 2024). "The results displayed that the level of SCNN1B and RBPMS2 was significantly reduced while the expression of NFE2L3 and CLDN2 was increased in GC tumor tissues compared to paracarcinoma tissues." (PMID 35137653, 2022). "CAPZA1, HLA-E, IMPA2, NFE2L3, PLEKHO1, SIGLEC1, and UBE2Z were expressed at higher levels in tumor tissues, whereas EMX2, FGL2, FUCA1, and GRB2 were expressed at lower levels in tumor tissues." (PMID 35127943, 2022). "Correlation analyses between NFE2L3 and IL- 2R/STAT5/NLRP3 related genes in TIMER, which were adjusted by tumor purity." (PMID 35664314, 2022). "PLAUR, PABPC1L, SLC16A12, NFE2L3, and KCNAB1 presented significantly different expression levels between tumor tissues and normal tissues." (PMID 35211477, 2021). "The nuclear factor erythroid 2-like 3 (NFE2L3) participates in constructing the basic-region leucine zipper family of transcription factors, which is an important factor in tumor progression." (PMID 35211477, 2021). "And using tissue sections for immunohistochemical staining, we can observe that NFE2L3 is mainly expressed in tumor cell nuclei, but not in normal pleural tissues." (PMID 35664314, 2022). "There was a significant negative correlation between the DNA methylation level of NFE2L3, the mRNA expression level and tumor cell stemness score in TCGA PANCAN cohort." (PMID 35846126, 2022). "Furthermore, the enhancement of tumor cell migration ability may be achieved by affecting the EMT, which process is dominated by NFE2L3, and knockdown of NFE2L3 inhibits Wnt/β-catenin signaling pathway." (PMID 33123284, 2020).
kidney disease (1 paper, 2019). "NFE2L3 encodes a transcription factor, nuclear factor erythroid 2-related factor 2 (NRF2), which has been widely studied for its cytoprotective functions, including in kidney disease." (PMID 31040861, 2019).
NFE2L3 also shares sentences with these, for which no sentence is quoted: endometriosis (4 papers); acute myeloid leukemia (2); bladder cancer (2); lung adenocarcinoma (2); lung carcinoma (2); lung squamous cell carcinoma (2); non-small cell lung carcinoma (2); rectal adenocarcinoma (2); renal cell carcinoma (2); skin cancer (2); adenoma (1); allergic disease (1); Alzheimer disease (1); astrocytoma (1); autoimmune thyroid disease (1); bladder urothelial carcinoma (1); bone osteosarcoma (1); breast adenocarcinoma (1); breast tumors (1); cardiovascular disease (1); cervical adenocarcinoma (1); colorectal (1); diabetes mellitus (1); digestive system cancer (1); dysplastic (1); esophageal adenocarcinoma (1); esophageal cancer (1); esophageal squamous cell carcinoma (1); fibrosarcoma (1); head and neck cancer (1).
A further 23 diseases each share a sentence with NFE2L3 in 1 paper.